CFL1 (cofilin 1)
Diseases named in the same sentence as CFL1 in open-access papers (continued):
Sharing a sentence is not in itself a finding about the gene and the disease.
gastric cancer (13 papers, 2016 to 2026). A primary or metastatic malignant neoplasm involving the stomach. "Elevated levels of CFL1 expression were also associated with tumour progression and increased invasiveness in breast, urothelial, prostate, and gastric cancer." (PMID 29581975, 2018). "In a study of the mechanism by which CFL1 regulates the development of cancer, CFL1 can induce epithelial interstitial transformation in gastric cancer cells through skeletal recombination, and silencing CFL1 can inhibit tumor metastasis." (PMID 35627108, 2022). "A further mechanism study demonstrated that EVs from cisplatin resistant gastric cancer cells communicate with cisplatin sensitive cells by translocating cofilin-1 into the mitochondria." (PMID 34678587, 2022). "It was also reported that CFL1 was closely related to the size, stage and differentiation of gastric cancer, especially to the invasion, and prognosis of gastric cancer." (PMID 33791303, 2021). "Further mechanism study demonstrated that cisplatin-resistant gastric cancer cell-derived exosomal RPS3 enhanced the chemoresistance of cisplatin-sensitive gastric cancer cells through the PI3K-Akt-cofilin-1 signaling pathway." (PMID 33644057, 2021). "In summary, we found that ROCK/PTEN/PI3K plays an important role in ZJW-reversed chemotherapeutic resistance of gastric cancer as a critical regulator of p-cofilin-1 dephosphorylation and mitochondrial translocation of cofilin-1." (PMID 30622602, 2018). "Given the role of p-cofilin-1 and cofilin-1 in drug resistance of cancer, we detected p-cofilin-1 and cofilin-1 protein expression levels in the four gastric cancer cell lines." (PMID 27872653, 2016). "To verify the role of cofilin-1 in the ability of ZJW to modulate DDP resistance in gastric cancer cell lines, we used RNA interference to reduce the expression of cofilin-1 in SGC7901/DDP cells and subsequently observed the effects of ZJW." (PMID 27872653, 2016). "A further mechanism study demonstrated that cisplatin-resistant gastric cancer cell-derived exosomal RPS3 could enhance the chemoresistance through the PI3K/Akt-mediated mitochondrial translocation of cofilin-1." (PMID 33644057, 2021). "Exosomal delivery of RPS3 protein may induce chemoresistance phenotypes from cisplatin-resistant gastric cancer cells to sensitive cancer cells by regulating the PI3K-Akt-cofilin-1 signaling pathway." (PMID 33644057, 2021). "After treatment with DDP for 24 h, the expression of p-cofilin-1 decreased significantly in BGC823 and SGC7901 cells, suggesting that DDP could induce p-cofilin-1 dephosphorylation and cofilin-1 activation in DDP-sensitive gastric cancer cell lines." (PMID 27872653, 2016). "We further observed that these effects of ZJW on DDP-resistant human gastric cancer cell lines could be reversed via transfection with cofilin-1-specific siRNA, or treatment with a PP1 and PP2A inhibitor." (PMID 27872653, 2016). "The results suggested p-cofilin-1 as an effective therapeutic target of gastric cancer." (PMID 27872653, 2016). "Our previous studies have proved that Zuo Jin Wan (ZJW), a traditional Chinese medicine (TCM) formula, could significantly enhance the sensitivity of cisplatin (DDP)-resistant gastric cancer cells to DDP by inducing apoptosis via mitochondrial translocation of cofilin-1." (PMID 30622602, 2018). "However, it remains unclear how ZJW inhibits the DDP resistance in gastric cancer cells involving the modulation of cofilin-1 activity." (PMID 30622602, 2018). "CFL1 showed higher disease specificity and pre-analytical stability than TAGLN2 across multiple non-gastric cancers and special-condition samples." (PMID 42192960, 2026). "Compared to adjacent normal gastric tissue, gastric cancer tissue exhibits upregulated expression of LIMK1, LIMK2, and Cofilin-1, while phosphorylated Cofilin-1 expression is downregulated." (PMID 37946061, 2024).
gastric cancer (continued). "All the findings demonstrated that cisplatin-resistant gastric cancer cells communicate with sensitive cells through the delivery key exosomal protein RPS3 and the activation of PI3K-Akt-cofilin-1 signaling pathway." (PMID 33644057, 2021). "All these findings demonstrated that cisplatin-resistant gastric cancer cells communicate with sensitive cells through the intercellular delivery of exosomal RPS3 and activation of the PI3K-Akt-cofilin-1 signaling pathway." (PMID 33644057, 2021). "We found that Cofilin1 (CFL1) expression was elevated in clinical gastric cancer specimens and correlated with biomarkers of EMT in BGC-823 gastric cancer cells." (PMID 28388575, 2017). "Certainly, degradation of F-actin to G-actin, the translocation of actin and cofilin-1 complexes to the mitochondria, and mitochondrial apoptosis were observed in DDP-resistant gastric cancer cells." (PMID 27872653, 2016). "At the same concentration, DDP could induce p-cofilin-1 dephosphorylation in DDP-sensitive gastric cancer cells but not in DDP-resistant gastric cancer cells." (PMID 27872653, 2016).
lung carcinoma (12 papers, 2011 to 2026). "The levels of CFL1 in sputum seem to present an impact on the natural history ofpatients with lung cancer." (PMID 29846436, 2018). "Considering the biological functions of cofilin-1 in cell motility, we evaluated the effects of cofilin-1 silencing in lung cancer metastases in vivo." (PMID 22087286, 2011). "Taken together, our works suggested Hhex repressed CFL1 phosphorylation in lung cancer cells." (PMID 34321041, 2021). "Sputum CFL1 was also able to identifycancer-free patients from patients with lung cancer." (PMID 29846436, 2018). "Research related to ABPs and lung cancer has mainly focused on twinfilin-1 (TWF1) and fascin-1 and on the relationships between VASP, profilin-1, and cofilin-1." (PMID 34194957, 2021). "However, CFL1 was also differentially abundant in our discovery set in lung cancer and therefore not specific to IDC." (PMID 33267867, 2020).
hepatocellular carcinoma (11 papers, 2021 to 2025). A malignant tumor that arises from hepatocytes. "Moreover, Cofilin-1 levels have been found to be increased in HBV-associated hepatocellular carcinoma and its levels were correlated with the severity of this liver disease." (PMID 37569584, 2023). "Hereafter, Cofilin-1 levels were related to the stage of liver fibrosis playing a key role in the progression of liver fibrosis toward hepatocellular carcinoma." (PMID 37569584, 2023). "Our findings demonstrated that miR-107 downregulation leads to hepatocellular carcinoma cell resistance in HDACi via a cofilin-1-dependent molecular mechanism and ROS accumulation." (PMID 33901009, 2021). "Moreover, both excessive macropinocytosis induced by OSI-027 and macropinocytosis inhibition via CFL1 depletion suppressed β-catenin-driven tumor growth in orthotopic hepatocellular carcinoma model mice." (PMID 40213667, 2025). "The overexpression of CFL1 inhibits NSCLC invasion but promotes metastasis in triple-negative breast cancer and hepatocellular carcinoma." (PMID 40149625, 2025). "Although the up-regulation of cofilin-1 was only detected in another salivary proteomics study on patients with PBC, two recent studies demonstrated the increase in cofilin-1 expression in hepatocellular carcinoma tissues." (PMID 39683940, 2024).
bladder cancer (9 papers, 2017 to 2025). "Recent works have shown that cofilin-1 is a direct target of miR-182-5p in human bladder cancer, and loss of miR-182-5p in bladder cancer can promote cofilin-1 expression." (PMID 35627108, 2022). "The loss of miR-182-5p in bladder cancer induced a high level of Cofilin 1, which promoted tumor cell proliferation, migration and invasion and tumorigenesis abilities." (PMID 30858759, 2019). "Consistent with our results, recent evidence showed an association between the nuclear localization of cofilin-1 and bladder cancer progression." (PMID 29844875, 2018). "Loss of miR-182-5p in bladder cancer can promotes Cofilin 1 expression, which may have a potential diagnostic and targeted therapy value for bladder cancer." (PMID 30858759, 2019). "According to reports, expression of CFL1 varies in carcinomas including prostate, breast, lung, colorectal, and oral cancers, and the expression of CFL1 was increased in bladder cancer tissues compared with the precancerous lesion (12, –14)." (PMID 34076143, 2021). "In this study, we demonstrated that Cofilin 1 is overexpressed in human bladder cancer tissues and cell lines compared with normal tissues or epithelial cells, which is consistent with our earlier research." (PMID 30858759, 2019). "The miR-182-5p/Cofilin 1 regulating axis reveals another potential mechanism of bladder cancer tumorigenesis." (PMID 30858759, 2019). "In eight human bladder cancer tissue samples, Cofilin 1 mRNA expression remarkably increased compared with homologous para-cancer tissues." (PMID 30858759, 2019). "In our earlier study, we reported that transcription factor TCF7L2 can binds to Cofilin 1 promoter and increases the gene expression in bladder cancer, which promotes the tumor progress." (PMID 30858759, 2019). "qRT-PCR and Western blotting analysis showed that Cofilin 1 expression was up-regulated in both bladder cancer tissues and cell lines compared with normal." (PMID 30858759, 2019). "Following with the demonstrating of TCF7L2/Cofilin 1 regulating pathway in bladder cancer, we uncovered another regulating mechanism of which Cofilin 1 promoting tumor progress through miR-182-5p/Cofilin 1 regulating axis." (PMID 30858759, 2019). "In our earlier study, we found that Cofilin 1 expresses much higher in human bladder cancer tissues than para-tumor tissues, and suppressing Cofilin 1 by siRNA can inhibit tumor cell growth." (PMID 30858759, 2019). "Here, we found that Cofilin 1 expression was higher in bladder cancer tissues than in paracancerous tissues." (PMID 29190896, 2017). "Cofilin 1 mRNA expression was higher in bladder cancer tissues than in corresponding paracancerous tissues." (PMID 29190896, 2017). "WB and IHC revealed that Cofilin 1 protein levels were higher in bladder cancer tissues than in corresponding paracancerous tissues." (PMID 29190896, 2017). "In this study, we found that Cofilin 1 expression was higher in bladder cancer tissues than in paracancerous tissues, which is consistent with previous results." (PMID 29190896, 2017). "Another study looking at human bladder cancer cell proliferation, migration and invasion, showed that increased miR-182–5p could potentially inhibit tumour growth by repressing cofilin-1 expression." (PMID 34678587, 2022). "We first proved that Cofilin 1 is a direct target of miR-182-5p in human bladder cancer." (PMID 30858759, 2019). "Here, we expect to further explore the role of Cofilin 1 regulated by miR-182-5p in bladder cancer." (PMID 30858759, 2019). "Furthermore, we found that transcription factor 7-like 2 (TCF7L2) enhances Cofilin 1 expression by binding to Cofilin 1 promoter in human bladder cancer, which can promote tumor progress." (PMID 30858759, 2019). "Therefore, decline expression of miR-182-5p contributes to the high level of Cofilin 1 in bladder cancer, for which enhanced the tumor cell proliferation, migration and invasion and tumorigenesis abilities." (PMID 30858759, 2019).
bladder cancer (continued). "Furthermore, we determined Cofilin 1 expression in two human bladder cancer cell lines, RT4 and T24." (PMID 30858759, 2019). "We firstly measured the expression of Cofilin 1 in human bladder cancer tissues and cell lines." (PMID 30858759, 2019). "Together, these results suggest that Cofilin 1 indeed promoted bladder cancer formation in vivo." (PMID 29190896, 2017). "Thus, TCF7L2 contributed to Cofilin 1-induced promotion of bladder cancer development by binding to the Cofilin 1 promoter and increasing its expression." (PMID 29190896, 2017). "Cofilin 1 also promoted bladder cancer growth in mouse xenograft experiments." (PMID 29190896, 2017). "Together, these results and previous studies suggest that Cofilin 1 may be a therapeutic target for bladder cancer." (PMID 29190896, 2017). "Furthermore, we discovered that transcription factor TCF7L2 bound to the Cofilin 1 promoter to increase its expression and promote the development of bladder cancer." (PMID 29190896, 2017). "Finally, the functions of Cofilin 1 in bladder cancer were confirmed in animal experiments." (PMID 29190896, 2017). "Downregulation of the cofilin-1 gene expression increases the percentage of apoptotic cells in the T24 and RT4 bladder cancer cell lines." (PMID 40362336, 2025). "Meanwhile we found that miR-182-5p can direct targets Cofilin 1 mRNA 3′UTR, and regulate the expression of Cofilin 1 in bladder cancer." (PMID 30858759, 2019). "Overexpression of Cofilin 1 promoted, while Cofilin 1 knockdown inhibited, proliferation, migration, and invasion in the T24 and RT4 bladder cancer cell lines." (PMID 29190896, 2017). "In this study, we confirmed that Cofilin 1 promoted the proliferation, migration, invasion, and adhesion capacities of T24 and RT4 bladder cancer cells while also inhibiting cell apoptosis." (PMID 29190896, 2017). "First, we measured Cofilin 1 expression in bladder cancer and paracancerous tissues and in the T24 and RT4 bladder cancer cell lines." (PMID 29190896, 2017). "Cofilin 1 mRNA expression in bladder cancer tissues and corresponding paracancerous tissues as well as T24 and RT4 bladder cancer cells was measured using RT-PCR." (PMID 29190896, 2017). "The results revealed that Cofilin 1, which was regulated by TCF7L2, promoted bladder cancer development." (PMID 29190896, 2017). "Together, these results indicate that Cofilin 1, which is regulated by TCF7L2, promotes bladder cancer development and progression." (PMID 29190896, 2017). "In this study, we first investigate that the absence of miR-182-5p in human bladder cancer promotes tumor growth by regulating the expression of Cofilin 1, an actin modulating-protein." (PMID 30858759, 2019). "We also examined the effects of Cofilin 1 in the T24 and RT4 bladder cancer cell lines." (PMID 29190896, 2017). "Here, we studied the effects of Cofilin 1 and TCF7L2 on bladder cancer." (PMID 29190896, 2017). "We suspect that Cofilin 1 is regulated by TCF7L2 and affects the development of bladder cancer." (PMID 29190896, 2017). "Similarly, Western blotting analysis revealed a higher Cofilin 1 protein level in bladder cancer tissues than in adjacent normal tissues." (PMID 30858759, 2019).
melanoma (9 papers, 2016 to 2025). A malignant, usually aggressive tumor composed of atypical, neoplastic melanocytes. "In this sense, we demonstrated an association between cofilin-1 levels and malignancy, measured by Breslow thickness, melanoma staging, mitotic index and presence of metastasis, in melanoma patients." (PMID 29844875, 2018). "Remarkably, these results support those obtained in our cohort of patients, suggesting that not only at protein level but also at mRNA expression level, cofilin-1 can be associated with a worse prognosis in melanoma." (PMID 29844875, 2018). "In this sense, we demonstrated increased cofilin-1 levels associated with malignant features of melanoma, such as BI and metastasis." (PMID 29844875, 2018). "Therefore, the levels of cofilin-1 can be associated with the melanoma outcome in this patient cohort." (PMID 29844875, 2018). "It was previously documented that cofilin-1 promotes cortical actin turnover at leader bleb necks in melanoma cells." (PMID 38702365, 2024). "Previously, we documented that cofilin-1 promotes cortical actin turnover at leader bleb necks in melanoma cells." (PMID 37961301, 2023). "(D) Western blot confirming CFL1, actin depolymerizing factor (ADF), and ADF + CFL1 RNAi in melanoma A375-M2 cells." (PMID 34169836, 2021). "In melanoma, it was shown that PlexinC1 is a tumor suppressor protein, as it inactivates CFL1, an actin-binding protein critical for cell adhesion and migration." (PMID 35008571, 2021). "In conclusion, our results are an important step toward the validation process of cofilin-1 as a prognostic biomarker in melanoma." (PMID 29844875, 2018). "Higher cofilin-1 levels were found in malignant melanoma (MM) with Breslow Index (BI)>2 vs MM with BI<2, melanoma in situ (MIS) and nevi and also in MM with metastasis vs MM without detected metastasis." (PMID 29844875, 2018). "This is the first study in a cohort of patients with melanoma that correlates cofilin-1 levels with malignant features and survival." (PMID 29844875, 2018). "As cofilin-1 has a dual function depending on its intracellular localization, we evaluated nuclear and cytoplasmic levels of cofilin-1 in melanoma and nevi samples by immunofluorescence." (PMID 29844875, 2018). "Melanoma cells with different degree of malignancy exhibited differential subcellular localization of cofilin-1 detected by immunocytofluorescence." (PMID 29844875, 2018). "Regarding the association of cofilin-1 levels and BI, a significant increased expression of CFL1 mRNA was observed in MM BI>2 compared with MM BI<2 (p<0.05) in the melanoma cohort from the TCGA Research Network." (PMID 29844875, 2018). "These evidences lead us to determine the levels and subcellular localization of cofilin-1 in melanoma human samples with different degrees of malignancy, in order to define this protein as predictor of advanced melanoma." (PMID 29844875, 2018). "We determined cofilin-1 levels in a retrospective cohort of patients with melanomas and benign lesions of melanocytes (nevi) by immunohistochemistry." (PMID 29844875, 2018). "Moreover, this study suggests that not only the higher levels of cofilin-1, but also its nuclear localization can be proposed as marker of worse outcome of patients with melanoma." (PMID 29844875, 2018). "Thus, besides the well-known function of cofilin-1 in migration when it is located at cytoplasm, we propose that cofilin-1 would be controlling other malignant features at the nucleus in melanoma." (PMID 29844875, 2018). "Furthermore, the analysis of cofilin-1 mRNA levels in the melanoma cohort from the TCGA Research Network supported the results obtained in our cohort of patients." (PMID 29844875, 2018). "Remarkably, cofilin-1 was also observed in the nucleus of more malignant melanomas." (PMID 29844875, 2018). "Moreover, we demonstrated an inverse correlation between cofilin-1 and survival, both at protein and mRNA expression levels in melanoma." (PMID 29844875, 2018).